MBNL1 (muscleblind like splicing regulator 1)
Description:
Mediates pre-mRNA alternative splicing regulation. Acts either as activator or repressor of splicing on specific pre-mRNA targets. Inhibits cardiac troponin-T (TNNT2) pre-mRNA exon inclusion but induces insulin receptor (IR) pre-mRNA exon inclusion in muscle. Antagonizes the alternative splicing activity pattern of CELF proteins. Regulates the TNNT2 exon 5 skipping through competition with U2AF2. Inhibits the formation of the spliceosome A complex on intron 4 of TNNT2 pre-mRNA. Binds to the stem-loop structure within the polypyrimidine tract of TNNT2 intron 4 during spliceosome assembly. Binds to the 5'-YGCU(U/G)Y-3'consensus sequence. Binds to the IR RNA. Binds to expanded CUG repeat RNA, which folds into a hairpin structure containing GC base pairs and bulged, unpaired U residues. Together with RNA binding proteins RBPMS and RBFOX2, activates vascular smooth muscle cells alternative splicing events. Regulates NCOR2 alternative splicing (By similarity).
Synonyms: EXP; KIAA0428; MBNL; EXP42; EXP40; EXP35
Tractability: Small molecule: it belongs to a druggable protein family. PROTAC: ubiquitination databases record sites on it; its protein half-life has been measured; a small molecule that binds it is known.
Gene: Protein-coding gene on chromosome 3 (152,243,828 to 152,465,781, forward strand). Ensembl gene ENSG00000152601.
Subcellular location: Nucleus; Cytoplasm; Cytoplasmic granule
Subcellular location (Human Protein Atlas): Nucleoplasm; Cytosol
Gene Ontology:
Molecular function: double-stranded RNA binding; protein binding; RNA binding; metal ion binding
Biological process: regulation of RNA splicing; RNA splicing; embryonic limb morphogenesis; in utero embryonic development; myoblast differentiation; nervous system development
Cellular component: cytoplasm; cytoplasmic stress granule; cytosol; nucleoplasm; nucleus
Genetic constraint (gnomAD): Loss-of-function variants: 7 observed, 41.49 expected, observed/expected ratio (o/e) 0.17, 90% interval 0.095 to 0.32. The upper end of that interval is the gene's LOEUF score, 0.32, which puts it in group 1 of 6, group 1 being the genes least tolerant of losing a copy. Missense variants: 288 observed, 492.03 expected, observed/expected ratio (o/e) 0.59, 90% interval 0.53 to 0.64. Synonymous variants: 161 observed, 174.14 expected, observed/expected ratio (o/e) 0.92, 90% interval 0.81 to 1.05.
Homologues: Orthologues: chimpanzee MBNL1 (100% identical), dog MBNL1 (99% identical), macaque MBNL1 (99% identical), pig MBNL1 (99% identical), rat Mbnl1 (99% identical), guinea pig MBNL1 (96% identical), mouse Mbnl1 (96% identical), tropical clawed frog mbnl1 (92% identical), rabbit MBNL1 (86% identical), zebrafish mbnl1 (82% identical), Drosophila melanogaster mbl (48% identical), Caenorhabditis elegans mbl-1 (23% identical). Paralogues in human: MBNL2 (66% identical), MBNL3 (63% identical), ZC3H10 (23% identical).
Diseases named in the same sentence as MBNL1 in open-access papers:
MBNL1 is named in the same sentence as 94 diseases in open-access papers, as found by Europe PMC text mining. Sharing a sentence is not in itself a finding about the gene and the disease. The quoted sentences say what the papers report.
myotonic dystrophy (72 papers, 2006 to 2026). An inherited progressive disorder affecting the muscles. "MBNL1 has been implicated in several neuromuscular disorders, with myotonic dystrophy (DM) being the most extensively studied conditions." (PMID 40565550, 2025). "The involvement of MBNL1 in the RBPMS-axis is intriguing as its dysregulation is associated with the pathology of myotonic dystrophy not only in skeletal and cardiac muscle but also potentially in gastrointestinal visceral SMCs." (PMID 41428739, 2025). "The MBNL1 gene encodes an RNA-binding protein, which regulates alternative mRNA splicing, and is known to be deregulated during myotonic dystrophy." (PMID 37554968, 2023). "Sequestration of MBNL1 in the nucleus by repeat-containing transcripts is associated with myotonic dystrophy." (PMID 37026480, 2023). "MBNL1 encodes an RNA-splicing protein with a well-characterized role in the pathogenesis of myotonic dystrophy that was recently associated with MLL-rearranged leukemia and colon cancer." (PMID 36142381, 2022). "Particularly, MBNL1 has been the main focus of intense studies over the past years due to its implication in the Myotonic Dystrophy (DM) pathogenic pathway." (PMID 36555788, 2022). "Most well-studied RBPs in muscle are associated with or causal for muscle diseases, notably CELF1 and MBNL1 (myotonic dystrophy), SMN (spinal muscular atrophy), TDP-43, and Rbm20 and Rbm24 (dilated cardiomyopathy)." (PMID 34685485, 2021). "In contrast, nuclear sequestration of MBNL1 in individuals with myotonic dystrophy causes the replacement of MBNL1 with Lin28." (PMID 33330108, 2020). "Nevertheless, our findings are consistent with a recent study, which suggested that DMPK is implicated in myotonic dystrophy by its dysregulation of MBNL1 and CELF1 mediated alternative splicing of the L-type calcium channel CACNA1S." (PMID 28152551, 2017). "MBNL1 sequestration induced mRNA mis-splicing is thought to contribute significantly to the varied phenotypes associated with myotonic dystrophy." (PMID 24039817, 2013). "Human MBNL1 is a key factor in the etiology of myotonic dystrophy (DM), a muscle wasting disease caused by the occurrence of toxic RNA molecules containing CUG/CCUG repeats." (PMID 22479576, 2012). "Muscleblind-like 1 (MBNL1) is an alternative splicing factor that is associated with the disease myotonic dystrophy (DM)." (PMID 21548961, 2011). "Indeed, it has been suggested that gastrointestinal dysfunction in myotonic dystrophy is associated with dysregulation of an MBNL1-regulated splicing programme in visceral smooth muscle cells." (PMID 37548402, 2023). "A designed autoregulated MBNL1 overexpression system, a prototype of a gene therapy tool, enables production of MBNL1 protein in cells with low activity of this protein caused by its pathogenic sequestration on toxic RNA containing CUG expansion in myotonic dystrophy (DM)." (PMID 36420218, 2022). "MBNL1 and MBNL2 are both required for late myogenic maturation in human skeletal muscle cells, and knockout of either Mbnl1 or Mbnl2 in mice serves as a model for myotonic dystrophy." (PMID 40944391, 2026). "HnRNP L is also a binding partner of MBNL1, and together they play a role in the pathophysiology of myotonic dystrophy." (PMID 40944391, 2026). "This scenario is disrupted in myotonic dystrophies due to diminished functional levels of MBNL1 and upregulation of hyperphosphorylated CUGBP1, which is predominantly found in DM1." (PMID 39903274, 2025). "Sequestration of MBNL1, an alternative splicing factor, leads to the missplicing of multiple pre-mRNAs in myotonic dystrophy." (PMID 35650428, 2022). "Two small molecules, pentamidine and Hoechst 33258 modulate alternative splicing in myotonic dystrophy by disrupting binding of the alternative splicing factor MBNL1 to expanded CUG in vitro and in vivo." (PMID 35650428, 2022).
myotonic dystrophy (continued). "Treatment with the anti-autophagic drug chloroquine was shown to upregulate MBNL1 and 2 proteins in animal DM models and patient-derived myoblasts, alleviating myotonic dystrophy phenotypes." (PMID 34948025, 2021). "For example, DM1 myotonic dystrophy, a trinucleotide repeat in the 3' UTR of the DMPK gene results in sequestration of the splicing regulator MBNL1, and this in turn causes defects in muscle gene expression, particularly alteration of splicing patterns." (PMID 33561245, 2021). "Such regulation is also disease relevant, as for example CUG repeat expansions found in patients with myotonic dystrophy sequester MBNL1 resulting in the abnormal stabilization of CELF1, disrupting normal RBP function." (PMID 34685485, 2021). "Here we demonstrate that the RNA alternative splicing factor MBNL1, which is sequestered in nuclear RNA foci by C(C)UG microsatellite expansions in myotonic dystrophy (DM), is essential for normal thymus development and function." (PMID 32332745, 2020). "In myotonic dystrophy, MBNL1 is sequestered into nuclear inclusions owing to uncontrolled binding to abnormal CUG repeat expansions in the 3′-untranslated region of dystrophia myotonica protein kinase mRNA." (PMID 31811140, 2019). "Of note, ATP2A1 is one of the multiple RNA targets that are misspliced as a result of MBNL1 sequestration in myotonic dystrophy (DM) muscles." (PMID 30688039, 2019). "This preferential expression of CELF1 over MBNL1, which mirrors that of the myotonic dystrophy model, most likely triggers the abnormal splicing of L-type calcium channels resulting in the reduced contractility in the Srf KO smooth muscle." (PMID 28152551, 2017). "In human, MBNL proteins, encoded by three members MBNL1, MBNL2 and MBNL3, are key splicing factors in the neuromuscular disease myotonic dystrophy (DM)." (PMID 23685613, 2013). "MBNL1 has been shown to play a crucial role in the pathology of myotonic dystrophy (Dystrophia myotonica, DM), an autosomal dominant disease, which is the most common form of muscular dystrophy affecting adults in humans." (PMID 22479576, 2012). "The sequestration of MBNL1 by expanded CUG and CCUG repeats is a major component in causing myotonic dystrophy." (PMID 21548961, 2011). "For example, increased inclusion of exon 5 of the splicing factor MBNL1 was detected in epithelial cells, a change that occurs in models of myotonic dystrophy and alters the intracellular localization of the protein from cytoplasmic to nuclear." (PMID 21876675, 2011). "Previous studies in myotonic dystrophy suggest that the expression of CUGexp transcripts, together with MBNL1 and CELF proteins and their downstream target genes need to be coordinated temporally and spatially for disease pathogenesis." (PMID 19680539, 2009). "MBNL1 function is also impaired in myotonic dystrophy (DM), a multisystemic disease characterized by myotonia, cataracts and muscle weakness, and a fly model of spinocerebelar ataxia 8 genetically interacted with Drosophila muscleblind mutants." (PMID 18286170, 2008). "The activity of the RNA splicing factor MBNL1 is altered in myotonic dystrophy (DM) patients." (PMID 32332745, 2020). "Myotonic dystrophy is caused by expansion of CTG and CCTG repeats in the DMLK and ZNF9 genes, respectively, that create aberrant RNAs that functionally sequester the splicing regulator MBNL1." (PMID 30057901, 2018). "Rau and colleagues hypothesized that in myotonic dystrophy, MBNL1 is sequestered, thereby permitting LIN28 to bind to the pre-miR-1 terminal loop and block miR-1 maturation." (PMID 30057901, 2018). "Here we focus on MBNL1, a splicing factormisregulated in the disease myotonic dystrophy." (PMID 27681373, 2016). "Because CUG-BP1 and MBNL1 have been shown to be antagonistic regulators of alternative splicing of a number of different targets from work done in the myotonic dystrophy field, we reasoned that CUG-BP1 CLIP tags would be also be good candidate targets for MBNL1 regulation." (PMID 19680539, 2009).
myotonic dystrophy (continued). "However, MBNL1 has an important role in RNA binding being recruited to the expansions of CUG repeats found in myotonic dystrophy in which the repeats form double-stranded RNA hairpins." (PMID 16390543, 2006). "Hence, we tested whether the release of MBNL1 from CCUG RNA foci upon rbFOX1 overexpression may correct splicing alterations typical of myotonic dystrophy." (PMID 29789616, 2018). "In mice, both brain-specific knockout of MBNL1 and MBNL2 and brain-specific expression of expanded CUG RNA in the myotonic dystrophy model resulted in the reduction of dendritic complexity and alteration of postsynaptic morphology." (PMID 39423233, 2024). "In the disease myotonic dystrophy, theactivities of MBNL1 protein and its paralogs, MBNL2 and MBNL3, are reduced viasequestration to toxic RNAs, resulting in a titration of MBNL proteins away fromtheir pre-mRNA substrates." (PMID 27681373, 2016). "In the case of myotonic dystrophy, the link between similar poly(CUG) RNA, MBNL1 sequestration, missplicing, and DM1 pathogenesis has been firmly established." (PMID 25593321, 2015). "To demonstrate the utility of AP-FRET in identifying RNA-protein interactions we first turned to the interaction of MBNL1 and DMPK RNA, which have been extensively studied in myotonic dystrophy." (PMID 24781112, 2014).
myotonic dystrophy type 1 (61 papers, 2012 to 2026). Steinert disease, also known as myotonic dystrophy type 1, is a muscle disease characterized by myotonia and by multiorgan damage that combines various degrees of muscle weakness, arrhythmia and/or cardiac conduction disorders, cataract, endocrine damage, sleep disorders and baldness. "The reversion to neonatal splicing pattern of exon 78 (transcripts E78-), due to the sequestration of nuclear MBNL1 and loss of function of the protein, contributes to the progressive dystrophic process in patients with myotonic dystrophy type 1." (PMID 33096920, 2020). "As expected, we were able to pull down proteins known to bind RNA such as CELF2, HNRNPM, and HDLBP, as well as RBPs involved in muscle diseases such as MBNL1, which plays a key role in the pathogenic mechanism of myotonic dystrophy type 1." (PMID 33338663, 2020). "Hnrnpl knockdown results in significant downregulation of Mbnl2 and upregulation of Mbnl1, two splicing factors that are linked to myotonic dystrophy type 1 (DM1)." (PMID 40944391, 2026). "Drosophila models exist for multisystemic disorders such as Myotonic Dystrophy Type 1 (DM1) that is caused by CTG expansions in the Dystrophia Myotonica Protein Kinase (DMPK) gene leading to the sequestration of RNA binding proteins such as MBNL1 in nuclear foci." (PMID 32630420, 2020). "Abnormally expanded CUG-repeats in the DMPK gene cause myotonic dystrophy type 1 (DM1) by sequestration of MBNL1 to nuclear RNA foci and by upregulation of another RNA-binding protein, CUG-binding protein 1 (CUGBP1)." (PMID 32054946, 2020). "MBNL1 is known to bind with high affinity to repeat sequences, which can lead to dysregulation of splicing, which in turn can lead to type 1 myotonic dystrophy (DM1), among other disorders." (PMID 37754104, 2023). "For example, in myotonic dystrophy type 1, MBNL1 was shown to be sequestered into CUG repeat RNA foci, and overexpression of MBNL1 in a mouse model was found to compensate its functional loss, resulting in the reversal of myotonia." (PMID 37461319, 2023). "Expanded CUG repeat RNA in the dystrophia myotonia protein kinase (DMPK) gene causes myotonic dystrophy type 1 (DM1) and sequesters RNA processing proteins, such as the splicing factor muscleblind‐like 1 protein (MBNL1)." (PMID 32449537, 2020). "MBNL1 also plays a significant role in myotonic dystrophy type 1 (DM1) muscle dysfunction." (PMID 39457375, 2024). "In the myotonic dystrophy type 1 (DM1) mouse model, treadmill running improved motor performance, forelimb grip strength and endurance, releasing Muscleblind‐like 1 (MBNL1) protein from myonuclear foci and improving mRNA alternative splicing." (PMID 39113268, 2024). "Myotonic Dystrophy Type 1 (DM1) is a genetic disorder caused by an expanded CTG repeat in the DMPK gene, leading to nuclear RNA foci and reduced MBNL1 levels." (PMID 39595972, 2024). "Myotonic Dystrophy type 1 (DM1) is caused by the expansion of RNA CUG repeats which bind and sequester MBNL1." (PMID 36555788, 2022). "In Myotonic Dystrophy type 1 (DM1), a non-coding CTG repeats rare expansion disease; toxic double-stranded RNA hairpins sequester the RNA-binding proteins Muscleblind-like 1 and 2 (MBNL1 and 2) and trigger other DM1-related pathogenesis pathway defects." (PMID 34593893, 2021). "Knockout of Mbnl1 results in pathology reminiscent of myotonic dystrophy type 1 (DM1) with abnormal terminal muscle differentiation." (PMID 32054946, 2020). "MBNL1 and MBNL2 associate and bind to expanded CUG and CAG repeats, which accumulate as discrete nuclear foci in both DM1 and DM2 (myotonic dystrophy type 1 and type 2), therefore suggesting their implication in these disorders." (PMID 27465358, 2016). "A clear line of evidence on repeat RNAs sequestering RBPs and influencing RNA splicing refers to myotonic dystrophy type 1 and 2 (DM1/DM2) where CUG- or CCUG-repeat RNA binds MBNL1–3, muscle or neuron-enriched RBPs." (PMID 39789319, 2025).
myotonic dystrophy type 1 (continued). "The overactivation of autophagy has been observed in MuSCs differentiated from induced pluripotent stem cells (iPSCs) derived from patients with myotonic dystrophy type 1 (DM1), in which muscleblind-like 1 (MBNL1) expression is reduced." (PMID 39925192, 2025). "However, disease-associated reduction of functional pool of MBNL1 results in exon 7a inclusion and NMD-based turnover of CLCN1 transcript which manifests in reduced chloride ion conduction and myotonia affecting skeletal muscles in myotonic dystrophy type 1 (DM1)." (PMID 32708277, 2020). "Cardiac conduction defects decrease life expectancy in myotonic dystrophy type 1 (DM1), a CTG repeat disorder involving misbalance between two RNA binding factors, MBNL1 and CELF1." (PMID 31829940, 2019). "Similar to myotonic dystrophy type 1, the poly(CUG)n RNA co-localizes with and sequesters the mRNA-splicing factor MBNL1, leading to missplicing of essential MBNL1-regulated mRNAs." (PMID 25593321, 2015). "However, in the CTG expansion disorder myotonic dystrophy type 1 (DM1) the opposite occurs, where overexpression of MBNL1 rescues the DM1 phenotype in myoblasts." (PMID 24293103, 2014). "It is believed that via this activity MBNL1 contributes to the formation of nuclear CUG RNA foci, and that nuclear but not cytoplasmic localization triggers pathogenesis in the CUG repeat disease Myotonic dystrophy type 1 (DM1)." (PMID 36585400, 2022). "Steinert disease, or myotonic dystrophy type 1 (DM1), is a multisystemic disorder caused by toxic noncoding CUG repeat transcripts, leading to altered levels of two RNA binding factors, MBNL1 and CELF1." (PMID 29716962, 2018). "Aberrant alternative splicing of MBNL1 and MBNL2 is characteristic of the foetal splice pattern reported in patients with the severe neuromuscular disease myotonic dystrophy type 1 (DM1; OMIM#160900)." (PMID 31116797, 2019). "In myotonic dystrophy type 1 (DM1), for instance, RNA foci formed of CAG·CTG repeat transcripts bind and inactivate the splicing factor muscleblind-like 1 protein (MBNL1)." (PMID 24129584, 2013). "Myotonic dystrophy type 1 (DM1) is one of the most common muscular dystrophies and can be potentially treated with antisense therapy decreasing mutant DMPK, targeting miRNAs or their binding sites or via a blocking mechanism for MBNL1 displacement from the repeats." (PMID 36769018, 2023).